PTGS2 (prostaglandin-endoperoxide synthase 2)
Diseases named in the same sentence as PTGS2 in open-access papers (continued):
Sharing a sentence is not in itself a finding about the gene and the disease.
Parkinson disease (15 papers, 2006 to 2025). A progressive degenerative disorder of the central nervous system characterized by loss of dopamine producing neurons in the substantia nigra and the presence of Lewy bodies in the substantia nigra and locus coeruleus. "In addition, Vim and Ptgs2 that are also associated with perivascular macrophages were upregulated, consistent with reports of increased Ptgs2 expression in Parkinson's disease patients and animal models." (PMID 29755323, 2018). "KEGG pathway analysis showed that the five pathways with the strongest positive correlation with PTGS2 expression: apoptosis, MAPK signaling pathway, Parkinson’s disease, AD and PPAR signaling pathway." (PMID 35783137, 2022). "Of particular note, these searches identified a clear direct connection between the primary target of Ibuprofen (PTGS2, or Cox2 – Ibuprofen is a nonspecific inhibitor that also targets Cox1), and Parkinson Disease." (PMID 22162991, 2011). "Moreover, plasma MALAT1, miR-125b, FOXQ1, PTGS2, and CDK5 could distinguish AD patients from controls, while only plasma MALAT1, miR-125b, and PTGS2 could discriminate AD patients from Parkinson’s disease patients." (PMID 36947499, 2023).
pulmonary fibrosis (15 papers, 2007 to 2025). Chronic progressive interstitial lung disorder characterized by the replacement of the lung tissue by connective tissue, leading to progressive dyspnea, respiratory failure, or right heart failure. "In fact, we previously reported that COX-2 null mice are susceptible to V2O5-induced lung fibrosis, which emphasized an important protective role for the PTGS2 gene during fibrogenesis." (PMID 17459161, 2007). "In animal models, PTGS2 deficient mice promoted bleomycin-induced pulmonary fibrosis." (PMID 35096012, 2021). "The actions of PTGS1 and PTGS2 are interconnected, collectively impacting the advancement of lung fibrosis." (PMID 40003932, 2025). "Results from studies conducted in recent years suggest that PTGS2 and its metabolites mediate a protective effect on pulmonary fibrosis." (PMID 35096012, 2021). "However, it is reasonable to infer that ferroptosis itself more likely represents a downstream pathway in ADAM17/PTGS2‐induced lung fibrosis during fibroblast activation." (PMID 40077919, 2025). "The cyclophosphamide may treat SLE-derived pulmonary fibrosis through interaction with PTGS2, which could be activated by p38MAPK." (PMID 36871016, 2023). "Our study demonstrates that ADAM17 regulates ferroptosis in lung fibroblasts to promote fibrosis development through PTGS2, suggesting a potential therapeutic target in ADAM17 for the treatment of lung fibrosis." (PMID 40077919, 2025). "Interestingly, APD downregulates ACSL4, PTGS2, and ROS while upregulating GPX4 and SLC7A11, indicating its role in inhibiting ferroptosis in pulmonary fibrosis." (PMID 38584671, 2024). "So PTGS2 may be a key treatment target and cyclophosphamide may have the treatment effect to the SLE-derived pulmonary fibrosis." (PMID 36871016, 2023).
endometrial cancer (14 papers, 2008 to 2025). Primary or metastatic malignant neoplasm involving the endometrium (mucous membrane that lines the endometrial cavity). "DHA also inhibited PGE2 production and PTGS2 expression in murine macrophages and cellular and animal models of endometrial cancer." (PMID 40941340, 2025). "PTGS2 was found to be induced by Akt and hypothesized to be active throughout the NF-κB pathway in mutated PTEN endometrial cancer cells (reaction 4)." (PMID 33250779, 2020).
Fever (14 papers, 2010 to 2025). Body temperature elevated above the normal range. "A total of 60 key target-symptom association pairs were detected, exemplified by the strongly association between fever and PTGS2 through the intermediary of Shu Di Huang." (PMID 37861529, 2023). "Compared with the normal group, the expression levels of IL6R, TNF-α, and PTGS2 were significantly higher in the fever group (p < 0.01)." (PMID 40430430, 2025). "The dispersion estimates results showed that the difference in the expression of IL6R, TNF-α and PTGS2 between the normal group and the fever group was statistically significant (p < 0.01)." (PMID 40430430, 2025). "Although infection is the primary cause of fever, endogenous heat sources such as IL-1β, TNF, IL-6, and PTGS2-induced prostaglandins also act on the thermoregulatory centers of allergic diseases." (PMID 35855823, 2022). "For example, the proteins PRSS1 and PTGS2, targeted by quercetin, luteolin, and stigmasterol, are important in curing fever." (PMID 32811894, 2020). "Low RMSD, RMSF, Rg, and SASA values as well as high intermolecular interactions indicated that GABBR2–saikosaponin C, GABBR2–baicalin, NFKBIA–glycyrrhizic acid, and PTGS2–lobetyolin complexes were quite stable, highlighting their potential as promising candidates for fever treatment." (PMID 38675434, 2024). "The fever group had significantly increased serum levels of TNF-α, IL-1β, IL-6 and PTGS2 (p < 0.05, p < 0.01) compared to the control group." (PMID 40430430, 2025).
nasopharyngeal carcinoma (14 papers, 2009 to 2024). A carcinoma arising from the nasopharyngeal epithelium. "PTGS2 gene polymorphisms are therefore strongly associated with gastric and nasopharyngeal cancers as well as other tumors." (PMID 36497451, 2022). "Previous studies have found that PTGS2 could mediate the interaction between cancer cells and myeloid-derived suppressor cells to promote nasopharyngeal carcinoma metastasis; PTGS2 overexpression was also associated with poor prognosis in NPC patients and led to chemotherapy resistance production." (PMID 36203533, 2022). "ZIC2 and OVOL1 may function in nasopharyngeal carcinoma through targeting significantly up-regulated genes (such as PTGS2, FN1, CXCL9 and CXCL10) in the Transcription factor-differentially expressed gene regulatory network (e.g., ZIC2→PTGS2 and OVOL1→CXCL10)." (PMID 27765529, 2017). "PTGS2, FN1, CXCL9, CXCL10, ZIC2 and OVOL1 might play roles in nasopharyngeal carcinoma." (PMID 27765529, 2017).
Cognitive impairment (13 papers, 2018 to 2026). Abnormal cognition is characterized by deficits in thinking, reasoning, or remembering. "PTGS2 is an important inflammatory mediator mostly expressed in the central nervous system; high PTGS2 expression is associated with neuronal damage and cognitive impairment." (PMID 37904435, 2023). "Both preoperative and postoperative administration of miR-214–3p suppressed its target gene prostaglandin-endoperoxide synthase 2 (PTGS2) and attenuated postoperative cognitive impairment." (PMID 40914484, 2025). "For instance, PTGS2, MAPT, and GABRA1 are critical targets of leukodystrophy and are associated with AD, neuropathic pain, and cognitive impairment in the T-D network." (PMID 36500385, 2022).
colon adenocarcinoma (13 papers, 2002 to 2024). "PTGS2 expression positively correlated with RUNX1 level in colon adenocarcinoma (COAD) samples using the TCGA-COAD dataset." (PMID 38778047, 2024). "To achieve this, we filtered the 785 colon adenocarcinoma patient data set using the differentially expressed genes involved in the bile acid pathway biosynthesis along with the ALOX5 and PTGS2 genes." (PMID 37458451, 2023).
colorectal adenoma (13 papers, 2005 to 2025). An adenoma that arises from the colon or rectum. "Risk estimates for the studied PTGS2 polymorphisms in relation to risk of colorectal adenomas and carcinomas." (PMID 25166592, 2014). "Risk estimates for PTGS2 haplotypes in relation to risk of colorectal adenomas and carcinomas." (PMID 25166592, 2014). "PTGS2 mRNA levels were significantly higher in intestinal tissues from colorectal adenoma and cancer cases than healthy controls." (PMID 38675376, 2024).
colorectal tumor (13 papers, 2009 to 2024). "PTGS2 has been considered an ideal target for colorectal tumor chemoprevention, but the cardiotoxicity associated to the specific PTGS2 inhibitor Celecoxib determined an unfavorable cost/benefit ratio for the chemoprevention of the normal population." (PMID 32168749, 2020). "Indeed, several bacterial species have been associated to CRC, and Streptococcus gallolyticus can infect colorectal tumors and has been linked to local IL1β and PTGS2 expression." (PMID 32168749, 2020). "Regarding colorectal tumors PTGS2, PTGES and PTGER3 were found up-regulated in many datasets." (PMID 26498686, 2015). "We studied the PG-pathway in gene expression databases and we found that PTGS2 (prostaglandin G/H synthase and cyclooxygenase) and PTGES (prostaglandin E synthase) are co-expressed in human colorectal tumors." (PMID 26498686, 2015). "PTGS2 and PTGES are both up-regulated in colorectal tumors when compared to normal tissue, while the PG receptor genes expression levels vary considerably, not correlating with the expression of PTGS2 and PTGES (not shown)." (PMID 26498686, 2015).
gout (13 papers, 2016 to 2025). A condition characterized by painful swelling of the joints, which is caused by deposition of urate crystals. "In IVW analysis, the results of the forest plots and scatter plots suggested that PTGS2 (p < 0.05, OR = 1.0010) promotes the pathological development of gout, with elevated PTGS2 levels increasing the risk of gout development." (PMID 40430440, 2025). "PTGS2 has shown high diagnostic value in gout, but its expression pattern in other inflammatory arthropathies has not been reported, suggesting that the gene has potential for targeted treatment of gout." (PMID 40606658, 2025). "Monosodium urate (MSU) crystals can increase the synthesis of prostaglandin E2 (PGE2) by increasing the expression of PTGS2, thereby causing or exacerbating inflammation such as gout." (PMID 39796505, 2024). "Our research showed a similar trend of increased PTGS2 expression in gout patients, suggesting that PTGS2 plays a significant role in gout-associated inflammation and pain and has the potential to be regarded as a diagnostic biomarker for gout." (PMID 40430440, 2025). "The results showed that low expression of key genes CXCL8, PTGS2 and IL10 were risk factors for gout." (PMID 40606658, 2025). "The results of the MR analysis with good sensitivity suggested a causal relationship between candidate genes (KCNA5, PTGS2, and TNF) and gout, in which high levels of PTGS2 increase the hazard of gout, while KCNA5 and TNF can diminish the occurrence of gout." (PMID 40430440, 2025). "In total, three candidate targets including KCNA5, PTGS2, and TNF were identified as having genetic causality with gout and were selected for further analysis as critical targets." (PMID 40430440, 2025). "RELA and NFKB1 are the core components of the classic NF-κB signaling pathway, directly involved in the regulation of various pro-inflammatory genes (such as CXCL8 and PTGS2), driving gout-related inflammatory responses." (PMID 40606658, 2025). "More importantly, high expression of PTGS2 in monocyte subtypes was detected in patients with gout flares, consistent with the MSU-induced PTGS2 expression in human monocytes." (PMID 38063198, 2023). "Collectively, these data underscore the pivotal role of AA metabolism during gout flares and highlight that monocyte subtypes with high PTGS2 expression are critical during gout flares." (PMID 38063198, 2023). "Our results demonstrate the upregulation of PTGS2 in monocyte subtypes that are involved in gout flares and remission." (PMID 38063198, 2023). "miR-16-5p, miR-128-3p, miR-20a-5p, and miR-155-5p can potentially influence pyroptosis and the occurrence and development of gout by affecting the expression of the PTGS2, CASP8, NFE2L2, and CD274 genes." (PMID 36291136, 2022). "Small molecule compounds with a strong binding affinity for PTGS2 were eventually used to develop a molecular docking model, which can be used to develop an efficient and reliable treatment strategy for gout." (PMID 36291136, 2022). "PTGS2, CASP8, NFE2L2, and CD274 were identified as key pyroptosis-related genes associated with gout." (PMID 36291136, 2022). "Therefore, the elevated expression of PTGS2 in circulating monocyte subtypes plays a pivotal role in gout flares and could underpin the molecular basis for the use of COX2 selective inhibitors as a first-line treatment for gout flares." (PMID 38063198, 2023). "Among these, pergolide exhibited the highest binding affinity with key gene-encoded proteins, suggesting potential therapeutic effects against gout through targeting CXCL8, PTGS2, and IL10." (PMID 40606658, 2025). "Among 329 gout-related genes identified, CXCL8, PTGS2, and IL10 emerged as key regulators involved in cell-cell adhesion, leukocyte activation, and NF-κB signaling." (PMID 40606658, 2025). "This study systematically elucidated the pivotal roles of CXCL8, PTGS2, and IL10 in gout pathogenesis, providing valuable molecular targets for therapeutic development." (PMID 40606658, 2025).
gout (continued). "In the LOO analysis, it was discovered that no single SNP strongly altered the holistic forest plot of KCNA5, PTGS2, and TNF for gout." (PMID 40430440, 2025). "Compared with the normal group, the PTGS2 and TNF expression levels were dramatically higher in the gout group, and the expression of KCNA5 was prominently lower in the gout group." (PMID 40430440, 2025). "The target genes of Terpine-4-ol, a main compound of ZP, were overlapped with the gouty arthritis-related genes such as NLRP3, PTGS2, CXCL8, IL6, TNF, IL1B, TLR4, and ALB." (PMID 39861092, 2024). "Experimental validation revealed that PTGS2 and NFE2L2 were significantly upregulated, and CASP8 and CD274 were significantly downregulated in gout." (PMID 36291136, 2022). "CXCL8 and PTGS2 were predominantly expressed in T/NK cells and myeloid cells, while IL10 was mainly expressed in myeloid cells, with all key genes showing elevated expression in the gout group." (PMID 40606658, 2025). "These PPI network analysis results showed that the key genes CXCL8, PTGS2 and IL10 played a key regulatory role in the PPI network, suggesting that they may play an important role in the occurrence and development of gout." (PMID 40606658, 2025). "Further PPI network analysis jointly identified three key genes, CXCL8, PTGS2, and IL10, which have a high degree of connectivity in the PPI network, suggesting that they may play a core regulatory role in the pathogenesis of gout." (PMID 40606658, 2025). "During the evolution from the acute phase to the remission phase of gout, KCNA5 in B cells and neutrophil cells was raised significantly, PTGS2 in B cells, macrophages, and monocytes was decreased significantly, and TNF in B cells and monocytes was also decreased significantly." (PMID 40430440, 2025). "The systemic immune and inflammatory responses of the body gradually decrease during the evolution of gout from the acute phase to the remission phase, though the KCNA5 level in B cells and neutrophil cells was raised, and PTGS2 and TNF in B cells, macrophages, and monocytes were decreased." (PMID 40430440, 2025). "KCNA5, PTGS2, and TNF were identified as crucial targets for Bi-Qi capsules in the treatment of gout, which might provide new evidence for the future clinical application of Bi-Qi capsules." (PMID 40430440, 2025). "Notably, the levels of PTGS2 (also known as cyclooxygenase 2; COX2), a key enzyme in prostaglandin biosynthesis, were significantly higher in gout flares among CMs, IMs, and NCMs." (PMID 38063198, 2023). "Therefore, we believe that KCNA5, PTGS2, and TNF may perform a key function in the treatment of gout with Bi-Qi capsules." (PMID 40430440, 2025).
liver cancer (13 papers, 2011 to 2024). An epithelial or non-epithelial malignant neoplasm that arises from the liver. "Over 50% of key targets, such as PTGS2, FOS, were involved in Hepatitis B, MAPK signaling pathways, which were closely associated with liver cancer." (PMID 37861529, 2023). "Zuogui Pill can improve different clinical symptoms in treating liver cancer, by regulating multiply targets like PTGS2 and FOS, participating in MAPK, IL-17 and TNF signaling pathways." (PMID 37861529, 2023). "The mechanistic studies implicate PTGS2 is overexpressed in liver cancer for promoting angiogenesis and inflammation." (PMID 34055017, 2021). "The results indicated that the key targets of the pathway in cancer were related to the therapeutic effect of anti-liver cancer activities, including SRC, EGFR, ESR1, PTGS2, and APP." (PMID 36561345, 2022). "Furthermore, the overexpression of PTGS2 was able to activate VEGF for tumor growth and diffusion, and EZ from CBC could treat liver cancer by inhibiting PTGS2 and VEGF." (PMID 34055017, 2021).
liver fibrosis (13 papers, 2017 to 2025). "PTGS2 also provides protection against non-alcoholic steatohepatitis, liver fibrosis, and supports gastric mucosal defense and renal homeostasis." (PMID 40474257, 2025). "PTGS2 drives liver fibrosis via three key mechanisms: under the induction of inflammatory factors, PTGS2 catalyzes PGE2 production, exacerbating liver inflammation." (PMID 40661312, 2025). "In our study, the results of network pharmacology indicated that the main relevant targets of LFP in the treatment of CCl4-induced liver fibrosis include PTGS2." (PMID 36059967, 2022). "Accordingly, these compounds of HQD may prevent the further development of liver fibrosis by alleviating liver inflammation through influencing the expression of PTGS2, PPARD, and PPARG." (PMID 34301291, 2021). "Additionally, there are 51 targets containing in both potential targets of DGLHD and liver fibrosis-associated targets, such as PTGS2, NF-κBp65, PPAR-γ, and PIK3CA, indicating the possible effects of DGLHD protecting against hepatic fibrosis." (PMID 29556199, 2018).